NFATC2 (nuclear factor of activated T cells 2)
Description:
Plays a role in the inducible expression of cytokine genes in T-cells, especially in the induction of the IL-2, IL-3, IL-4, TNF or GM-CSF. Promotes invasive migration through the activation of GPC6 expression and WNT5A signaling pathway. Is involved in the negative regulation of chondrogenesis. Recruited by AKAP5 to ORAI1 pore-forming subunit of CRAC channels in Ca(2+) signaling microdomains where store-operated Ca(2+) influx is coupled to calmodulin and calcineurin signaling and activation of NFAT-dependent transcriptional responses.
Synonyms: NF-ATp; NFAT1; NFATP; JCOSL
Tractability: Small molecule: a structure with a bound ligand is known. PROTAC: UniProt records ubiquitination sites on it; ubiquitination databases record sites on it; its protein half-life has been measured.
Safety:
Unwanted effects reported when the protein is acted on. In parentheses: how it was acted on, where the effect was seen, and who reports it.
hypersensitivity (source: ClinPGx)
hypersensitivity to asparaginase (source: ClinPGx)
Gene: Protein-coding gene on chromosome 20 (51,386,957 to 51,562,831, reverse strand). Ensembl gene ENSG00000101096.
Subcellular location: Cytoplasm; Nucleus
Subcellular location (Human Protein Atlas): Cytosol; Nucleoplasm
Pathways (Reactome):
Immune System: CLEC7A (Dectin-1) induces NFAT activation; Calcineurin activates NFAT; FCERI mediated Ca+2 mobilization
Developmental Biology: Differentiation of naive CD4+ T cells to T helper 2 cells (Th2 cells)
Gene expression (Transcription): RUNX1 and FOXP3 control the development of regulatory T lymphocytes (Tregs)
Gene Ontology:
Molecular function: 14-3-3 protein binding; molecular adaptor activity; phosphatase binding; protein binding; sequence-specific double-stranded DNA binding; DNA binding; DNA-binding transcription factor activity; DNA-binding transcription factor activity, RNA polymerase II-specific; RNA polymerase II cis-regulatory region sequence-specific DNA binding; chromatin binding; DNA-binding transcription activator activity, RNA polymerase II-specific; DNA-binding transcription repressor activity, RNA polymerase II-specific; sequence-specific DNA binding; transcription cis-regulatory region binding
Biological process: B cell receptor signaling pathway; cartilage development; cell migration; DNA damage response; negative regulation of vascular associated smooth muscle cell differentiation; positive regulation of B cell proliferation; positive regulation of DNA-templated transcription; response to xenobiotic stimulus; calcineurin-NFAT signaling cascade; positive regulation of transcription by RNA polymerase II; regulation of DNA-templated transcription; regulation of transcription by RNA polymerase II; negative regulation of transcription by RNA polymerase II; positive regulation of gene expression
Cellular component: cytoplasm; cytosol; nucleoplasm; nucleus; transcription factor AP-1 complex; chromatin; transcription regulator complex; ribonucleoprotein complex
Genetic constraint (gnomAD): Loss-of-function variants: 21 observed, 82.88 expected, observed/expected ratio (o/e) 0.25, 90% interval 0.18 to 0.37. The upper end of that interval is the gene's LOEUF score, 0.37, which puts it in group 1 of 6, group 1 being the genes least tolerant of losing a copy. Missense variants: 1,139 observed, 1,251.3 expected, observed/expected ratio (o/e) 0.91, 90% interval 0.87 to 0.96. Synonymous variants: 564 observed, 539.74 expected, observed/expected ratio (o/e) 1.04, 90% interval 0.97 to 1.12.
Gene-disease validity (ClinGen):
ClinGen rates the evidence that NFATC2 causes each of these diseases.
congenital heart disease (autosomal dominant): Disputed. A heart disease that is present at birth.
Homologues: Orthologues: macaque NFATC2 (98% identical), chimpanzee NFATC2 (98% identical), pig NFATC2 (94% identical), dog NFATC2 (93% identical), guinea pig NFATC2 (91% identical), rat Nfatc2 (90% identical), mouse Nfatc2 (89% identical), rabbit NFATC2 (87% identical), tropical clawed frog nfatc2 (67% identical), zebrafish nfatc2a (52% identical). Paralogues in human: NFATC1 (40% identical), NFATC3 (38% identical), NFATC4 (33% identical), NFAT5 (24% identical).
Diseases named in the same sentence as NFATC2 in open-access papers:
NFATC2 is named in the same sentence as 181 diseases in open-access papers, as found by Europe PMC text mining. Sharing a sentence is not in itself a finding about the gene and the disease. The quoted sentences say what the papers report.
breast carcinoma (50 papers, 2007 to 2025). "The expression of CTHRC1 was found to be induced by NFATC2, which has been implicated in the pathogenesis of many solid tumors, including pancreatic, lung, and breast cancers." (PMID 26918341, 2016). "Glypican (GPC)-6 (GPC6) was reported to modulate invasive migration in breast cancer cells and was transcriptionally regulated by NFATc2." (PMID 39436410, 2025). "In ovarian cancer, it can target ORP4, which is associated with proliferative activity; In breast cancer, it can decrease the expression of NFATc2 to inhibit tumor growth and metastasis." (PMID 36133816, 2022). "In the four-gene prognostic signature, EXOC6, GPC6, and NFATC2 were correlated with aggression of breast cancer." (PMID 35265226, 2022). "NFAT1, also named NFATp or NFATc2, is overexpressed and hyperactivated in human cancers, including breast cancer." (PMID 26461225, 2015). "Thus, the activation of NFATc2 promotes breast cancer metastasis by upregulation of ADAM metalopeptidase with thrombospondin type 1 motif 6 (ADAMTS6) expression." (PMID 40078961, 2025). "Consequently, activated NFATc2 escalates breast cancer metastasis by upregulating ADAM metallopeptidase with thrombospondin type 1 motif 6 (ADAMTS6) expression." (PMID 37892239, 2023). "So, we suspected that NFATc2 might be the key factor in OSW‐1‐induced cell death on breast cancer cells." (PMID 32515123, 2020). "Moreover, enhanced level of Nfatc2 and Nfkb1 positively correlated with Ets1 expression in the human breast cancer specimens." (PMID 30467308, 2018). "Moreover, it has been unveiled that NFATC2 is negatively correlated with Stat5 and that these two transcription factors may significantly influence the progression of breast cancer." (PMID 35265226, 2022). "Next, we tested whether differential expression of NFATc2 or NF-κBs has any correlation with Ets1 expression in human breast cancer specimens by analyzing The Cancer Genome Atlas (TCGA) database that provide unbiased large-scale transcriptome data for various human cancer." (PMID 30467308, 2018). "The findings suggest that TRPV6 activation enhances NFATc2’s transcriptional activity by modulating the phosphorylation of NFATc2IP, thereby promoting ADAMTS6 expression and facilitating metastasis in breast cancer." (PMID 40078961, 2025). "Among the amplification driver genes, NRAS (in breast carcinoma and skin melanoma), ERBB2 (in gastric carcinoma, esophageal carcinoma), and NFATC2 (in ovarian carcinoma and pancreatic carcinoma) were identified in more than one cancer type." (PMID 38195844, 2024). "We demonstrated that the transcription factor NFAT1 (NFATc2) exerts a pro-invasive function, whereas NFAT3 (NFATc4) has anti-invasive properties limiting the aggressiveness of primary NFAT3-expressing luminal breast cancer cells." (PMID 32488182, 2020). "NFATC1 binds to the ITGB3 promoter in osteoclast precursor cells, while NFATC2 and NFAT5 promote ITGA6/ITGB4-mediated cell invasion in breast cancer." (PMID 31730483, 2019). "In summary, our study suggests that the crosstalk between NFATc2, NFKB1/RELA, and CRE region regulates Ets1 gene transcription in metastatic breast cancer cells." (PMID 30467308, 2018). "Compared with the less metastatic breast cancer cells, metastatic breast cancer cells (MDA-MB-231) show open chromatin configurations in the CRE, which facilitates direct binding of NFATc2 and/or NFKB1/RELA complex to trans-activate Ets1 transcription." (PMID 30467308, 2018). "Compared with less metastatic cells (MCF-7), metastatic breast cancer cells (MDA-MB-231) have relatively open chromatin structure on the CRE, which facilitates direct binding of NFATc2 and NFKB1/RELA to enhance Ets1 expression and invasiveness of metastatic breast cancers, accordingly." (PMID 30467308, 2018).
breast carcinoma (continued). "Indeed, NFAT1 (NFATc2) exerts a pro-invasive function and is mainly expressed in the triple-negative subtype, whereas NFAT3 (NFATc4) has anti-invasive properties, limiting the aggressiveness of primary NFAT3-expressing luminal breast cancer cells." (PMID 35847954, 2022). "In addition, the GEPIA web tool analysis showed that the mRNA levels of NFAT1 (NFATC2) were positively correlated with the expression of PD-L1 (CD274) in ccRCC, lung adenocarcinoma, bladder cancer, liver cancer, prostate cancer, pancreatic cancer, and breast cancer." (PMID 35081978, 2022).
melanoma (33 papers, 2014 to 2025). A malignant, usually aggressive tumor composed of atypical, neoplastic melanocytes. "The TF NFATc2 expressed in MITFlow melanoma cells was linked to an epithelial–mesenchymal transition (EMT)-like program of melanoma cells associated with myc, FOX1 and EZH2 expression." (PMID 37347257, 2023). "Treatment of melanoma cells with zoledronic acid suppressed nuclear NFATc2 associated with increased cytoplasmic NFATc2 levels." (PMID 30710146, 2019). "Recent experiments showed that Nfatc2 deficiency in the background stroma impaired establishment of B16 melanoma tumors in the lung, suggesting a role for this protein in tumor-associated inflammation." (PMID 24945807, 2014). "NFATc2 (nuclear factor of activated T cells 2) is reported to be an intrinsic regulator of melanoma dedifferentiation." (PMID 38980592, 2025). "Many researches demonstrated the critical functions of NFATC2 in cancers such as colon cancer, pancreatic cancer, lung adenocarcinoma, melanoma, and other cancers." (PMID 35265226, 2022). "In melanoma, an actionable axis linking NFATc2 to EZH2 was shown to control the EMT-like program of melanoma cells, while inhibition of EZH2 downregulated EMT-related gene expression." (PMID 34199763, 2021). "Recent studies demonstrated that NFATc2 can also be activated and execute oncogenic activity in multiple malignancies, including melanoma, pancreatic and breast cancers." (PMID 32041943, 2020). "Taken together these results indicate that NFATc2 and EZH2 represent potentially relevant actionable targets in melanomas belonging to different mutational subsets." (PMID 30710146, 2019). "Collectively, these results support a model where an NFATc2/c-Myc/FOXM1/EZH2 axis regulates the EMT-like/invasive program of melanoma cells." (PMID 30710146, 2019). "In fact, NFATc2 targeting reversed melanoma de-differentiation, promoted upregulation of MITF and of melanocyte-lineage-specific antigens, and downregulated the stemness-related marker CD271." (PMID 30710146, 2019). "By western blot analysis in 12 melanoma cell lines we tested expression of NFATc2, of several EMT-related proteins as well as of AXL and MITF, the prototypic markers of the alternative invasive/proliferative transcriptional programs of melanoma." (PMID 30710146, 2019). "Here we show that the EMT-like transcriptional program of melanoma cells is indeed controlled by NFATc2 acting on c-Myc, FOXM1 and EZH2 and that NFATc2 regulates melanoma migratory and invasive activity in vitro, and tumor growth in vivo." (PMID 30710146, 2019). "Stable silencing of NFATc2 impaired melanoma cell proliferation in vitro and tumor growth in vivo in SCID mice." (PMID 30710146, 2019). "In NFATc2+ EZH2+ melanoma cell lines pharmacological co-targeting of NFATc2 and EZH2 exerted strong anti-proliferative and pro-apoptotic activity, irrespective of BRAF or NRAS mutations and of BRAF inhibitor resistance." (PMID 30710146, 2019). "Taken together, these data indicate that NFATc2 is expressed in melanoma cells showing an EMT-like transcriptional program." (PMID 30710146, 2019). "Analysis of a panel of melanoma cell lines indicated co-expression of NFATc2 and of EZH2, thus supporting the rationale for testing the potential anti-tumor effects of pharmacological co-targeting." (PMID 30710146, 2019). "Expression of NFATc2, MITF, AXL, ZEB1, SNAI1 (encoding SNAIL), and CDH2 (N-Cadherin) was then evaluated at the mRNA level, by qPCR, in a larger panel of 30 melanoma cell lines." (PMID 30710146, 2019). "NFATc2 silencing by shRNA or treatment of melanoma cells with inhibitors of NFATc2 (AM404), c-Myc (10058-F4), FOXM1 (Siomycin A) or EZH2 (GSK126) reduced significantly migratory activity, by wound healing assay, and invasive ability." (PMID 30710146, 2019). "In fact, by analysis of melanoma cell lines, TCGA data and melanoma lesions, we found that NFATc2 defines a subset of melanomas characterized by constitutive expression of a large set of EMT-related genes." (PMID 30710146, 2019).
melanoma (continued). "Tumor nodules from Me71 melanoma cells with stably silenced NFATc2 showed significant reduction in both volume and weight compared to nodules from control transfectants, at day +55 after s.c. injection in SCID mice." (PMID 30710146, 2019). "Taken together these results indicate that NFATc2 controls an EMT-like/invasive melanoma transcriptional program." (PMID 30710146, 2019). "As a further approach, we used zoledronic acid, a third generation biphosphonate with significant anti-melanoma activity that inhibits the GSK-3β-dependent NFATc2 nuclear stabilization pathway." (PMID 30710146, 2019). "Other genes correlating with CTHRC1 expression in melanoma cell lines included the transcription factor NFATC2 and ITGB3." (PMID 26918341, 2016). "At the protein level, FN1, ITGB3, and NFATC2 were expressed in a manner similar to CTHRC1 in our panel of melanoma cell lines." (PMID 26918341, 2016). "Targeting NFATc2 by si/shRNA or by an inhibitor known to downregulate EMT-related markers inhibited the migratory and invasive capacity of melanoma cells in vitro and in vivo, which is caused by an altered expression of downstream molecules thereby reversing the EMT-like program." (PMID 37347257, 2023). "We knew that Myc is suppressed by NFATc2 targeting in melanoma." (PMID 30710146, 2019). "Melanoma cell lines belonging to distinct mutational groups (BRAF-mutant, NRAS-mutant, or wild type for both BRAF and NRAS) co-expressed NFATc2 and EZH2 supporting the rationale for testing the potential anti-tumor effects of pharmacological co-targeting." (PMID 30710146, 2019). "In the investigated melanoma lesions NFATc2 expression showed an association with EMT-markers and lack of MITF, but at least one exception was found, in agreement with the notion that EMT and melanoma de-differentiation are multi-step processes with several intermediate phenotypic profiles." (PMID 30710146, 2019). "A significant increase in melanoma apoptosis, compared to treatment with single agents, was obtained even by association of EZH2 inhibitor GSK126 with the GSK-3β inhibitor AR-014418, in agreement with the role of GSK-3β in NFATc2 regulation." (PMID 30710146, 2019). "In vitro and in vivo melanoma growth were significantly impaired by stable silencing of NFATc2." (PMID 30710146, 2019). "Our results show that NFATc2 is a relevant regulator of the EMT-like melanoma program." (PMID 30710146, 2019). "By building upon this initial evidence we tested the hypothesis that NFATc2 could be involved in controlling the EMT-like/invasive melanoma program by regulating a specific set of downstream molecular targets." (PMID 30710146, 2019). "Furthermore, CTHRC1 was recognized as an important mediator of melanoma cell migration and invasion, providing together with its regulators—NFATC2, TGFβ, and BRAF—attractive therapeutic targets against metastatic melanomas." (PMID 26918341, 2016). "The TF NFATc2 is frequently expressed and transcriptionally active in cutaneous melanoma, and we found that it may behave as a master gene controlling transcriptional programs of melanoma cells." (PMID 30710146, 2019). "Indeed, MEK inhibition by PD0325901 reduced NFATc2 protein expression in two melanoma cell lines." (PMID 30710146, 2019). "On this basis and according to available evidence on regulation of FOXM1 by Myc and on regulation and roles of FOXM1 and EZH2 in EMT, we tested the hypothesis that the EMT-like program of melanoma cells could be regulated by an axis connecting NFATc2 to EZH2, through c-Myc and FOXM1." (PMID 30710146, 2019). "In addition, inhibition of NFATc2 by AM404 or zoledronic acid, or the GSK-3β inhibitor AR-014418 in association with the EZH2 inhibitor GSK126-induced significant anti-proliferative and pro-apoptotic effects on melanoma cell lines." (PMID 30710146, 2019).